AHR (aryl hydrocarbon receptor)
Diseases named in the same sentence as AHR in open-access papers (continued):
Sharing a sentence is not in itself a finding about the gene and the disease.
cancer (continued). "Moreover, in triple negative breast cancers, AhR was more active in the ALDH1high cancer stem cell subpopulation, and was reported to increase stem cell marker expression and properties, and chemoresistance." (PMID 35681770, 2022). "When considering molecular targets relevant for cancer prevention, it has been shown that the flavonoids quercetin and kaempferol interact with the transcription factor aryl hydrocarbon receptor, which has a prominent role in the development of chemical-induced cancer." (PMID 36142391, 2022). "The AhR may impact cell proliferation through diverse mechanisms, which have been studied primarily in cancer cells." (PMID 36077780, 2022). "However, several studies have indicated that the expression of AhR maintained and enhanced the stemness of cancer stem cells." (PMID 35987825, 2022). "AHR activation modulates the invasive properties of cancer cells." (PMID 36292946, 2022). "However, inhibition of KAT I or KAT II in cancer therapy is desirable as a way of limiting KA formation and hence AhR activation." (PMID 36286592, 2022). "Kynureninases and AhR antagonists represent cutting edge immunometabolic compounds that could safely magnify the benefit of cancer immunotherapy." (PMID 35173722, 2022). "Natural AhR ligands induce an AhR-dependent apoptosis in cancer cells." (PMID 36077780, 2022). "AhR is a transcription factor highly expressed in various cancer types including PDAC." (PMID 35997090, 2022). "Kyn, the major metabolism of Trp degradation, could activate aryl hydrocarbon receptor (AhR), inhibit antitumor immune, and accelerate the survival of cancer cells." (PMID 36118672, 2022). "Therefore, AhR has been studied as an interesting target of pollutant-induced cancers and, specifically, natural products, among which flavonoids, have seized the attention of the scientific community in these regards." (PMID 35163492, 2022). "There is extensive support from cell culture and in vivo studies indicating that the AhR is a target for breast cancer therapy and human clinical trials using the AhR ligand “aminoflavone” have been carried out for treating breast and other cancers." (PMID 36428667, 2022). "This places AhR at the intersection between racial/ethnic and socioeconomic disparities in toxin exposure in under-resourced neighborhoods and cancer stemness, undermining response to cancer therapy, worsening the riskscape that an individual must navigate." (PMID 36588678, 2022). "Of interest, a pantissue AHR signature has recently highlighted 3-IAld among the metabolites downstream of the L-amino acid oxidase catabolism of Trp that were associated with AHR-driven cancer cell motility and immunosuppression." (PMID 35722100, 2022). "Nevertheless, AhR activation is not the only factor that is believed to underlie the failure of IDO1 inhibitors in cancer treatment." (PMID 36163134, 2022). "The underlying mechanism could be that Fn-derived formate activates the aryl hydrocarbon receptor signaling, because the aryl hydrocarbon receptor is involved in regulating the stemness of cancer cell." (PMID 36523635, 2022). "This loop is autoregulated by AHR-dependent elevation of the AHR repressor, and CYP1A1 and CYP1B1 enzymes that metabolize kynurenine ligands to decrease their bioavailability, thus forming a cancer progression circuit where AHR-regulated CYP1B1 levels correlate with AHR activity." (PMID 36077068, 2022). "Indeed, in prostatic cancer cells, kynurenine accumulation in response to TDO2 induction was shown to activate an AhR-cMYC-ABC transporter axis thereby providing cancer cells with chemoresistance." (PMID 35681770, 2022). "As a chemopreventative agent in cancer, curcumin has been shown to decrease AHR levels." (PMID 35405942, 2022).
cancer (continued). "A pharmacologically optimized human kynureninase is currently moving toward clinical development for the treatment of cancers where Trp-Kyn-AhR pathway play a significant immunosuppressive role through Kyn production, and those independently of both IDO1 and TDO2 overexpression." (PMID 35173722, 2022). "Finally, novel inhibitors targeting the Trp-Kyn-AhR pathways, such as navoximod, tryptophan mimetics, kynurenine-degrading enzymes, and aryl hydrocarbon receptor antagonists, are also explored in cancer therapy based on MDSCs." (PMID 35585567, 2022). "The Trp-Kyn-AHR pathway executes an essential role in the regulation of T cell immunity in cancer." (PMID 34659216, 2021). "Activation of AhR is associated with the loss of cell contact inhibition and changes to the extracellular matrix, and extensive studies have demonstrated that this activation induces epithelial to mesenchymal transition (EMT) in various cancers." (PMID 34680327, 2021). "Consistency has been observed between AhR activity and expression in some cancers (7/33)." (PMID 34290693, 2021). "Thus, the use of PKCα inhibitors to control AhR-related epigenetic regulation is a promising potential method to prevent acquired resistance to HDACi-based cancer treatments." (PMID 33451095, 2021). "This research is the first to investigate the immunotherapeutic value of AhR in 33 human cancers." (PMID 34290693, 2021). "Subsequent activation of AhR might produce oxidative stress and ROS, resulting in cancer induction and immune function suppression." (PMID 33800744, 2021). "Finally, various drugs used for purposes other than treating cancer display AhR-antagonist activity." (PMID 33451095, 2021). "Given that the activity of IL4I1 is independent of the KP and can limit antitumor immune cell response, inhibiting the formation of KYNA metabolite either via the KP or through IL4I1 gene reaction may be necessary to block the activation of AhR in cancer." (PMID 34680327, 2021). "Additionally, AhR-activated miRNAs can serve as valuable biomarkers of diseases, notably cancer progression or suppression and chemical exposure." (PMID 34746229, 2021). "This indicates IDO inhibitors and AhR antagonists as a new therapeutic solution in cancer therapy." (PMID 34201791, 2021). "Apigenin (a flavone), baicalein (a flavone), chrysin (a flavone), diosmetin (a flavone) and quercetin (a flavonol) are shown to activate the AhR while keampferol (a flavonol), galangin (a flavonol) and naringenin (a flavanone) are demonstrated to antagonise the AhR and exhibit anti-cancer effects." (PMID 34249001, 2021). "In addition to the overexpression of AhR mRNA and protein, the activity of the receptor has been found to be significantly elevated in various types of cancer." (PMID 33451095, 2021). "The current findings suggested that high AhR expression might modulate innate immunity in some cancers by activating Toll-like receptor pathways." (PMID 34290693, 2021). "Although AhR expression was not closely related to clinical parameters, it was strongly associated with survival in some cancers (KIRC, LGG and PAAD)." (PMID 34290693, 2021). "The proposed molecular mechanism of PCDD/PCDFs envisages the binding of the dioxin to the aryl hydrocarbon receptor, which is a transcriptional regulator of cell growth, migration, and invasion of cancer cells, as well as inflammation and immune suppression in several cancers." (PMID 34638358, 2021). "These trials underscore the importance of considering AhR as a next-generation cancer treatment." (PMID 33451095, 2021). "TKis could be used to modulate DC immunogenic activity and may potentially be applied to DC-based cancer immunotherapy as a complement to AhR or IDO inhibitors." (PMID 33451095, 2021). "AhR can be effectively modulated by its ligands, e.g., selective AhR modulators, resulting in either agonistic or antagonistic effects on many of the hallmarks of cancer." (PMID 34094928, 2021).
cancer (continued). "Recent studies indicate that AhR-kynurenic acid interaction may be relevant for maintaining the immunosuppressive microenvironment in several cancer types." (PMID 33499346, 2021). "Furthermore, Toll-like receptor signaling pathways were enriched in the high AhR-expressing groups of some cancers." (PMID 34290693, 2021). "Activation of AhR may facilitate cancer cell proliferation, tissue invasion, metastasis, and angiogenesis." (PMID 34680327, 2021). "Overall, triggering of AhR for cancer treatment shows great potential." (PMID 33451095, 2021). "In addition, we recently identified the L-amino acid oxidase interleukin-4-induced-1 (IL4I1) as a novel and very potent upstream regulator of AHR, and we showed that IL4I1 associates more frequently with AHR activity than IDO1 or TDO2 in cancer." (PMID 33920868, 2021). "The next structure responsible for pro-tumoral effect of TRP metabolites is AhR and its inhibition may serve as a target in cancer treatment." (PMID 34071442, 2021). "This suggests that the regulation of basal Akt activity by the AhR may be cell-type specific and/or be reflective of differences between primary and cancer cells." (PMID 34848742, 2021). "Kynurenine pathway is dependent on Aryl hydrocarbon receptor (AhR) to some extent; its upregulation may lead to cancer progression via down-regulating T-cell phenotype, and then suppressing antitumor immune responses." (PMID 34413774, 2021). "Overall, this work provides evidence to elucidate the immunotherapeutic role of AhR in cancer, which may be helpful for further functional experiments." (PMID 34290693, 2021). "While it is beyond the scope of this review to discuss the large and exciting area of AHR and cancer, it may be noted here that there is a strong link between AHR’s effects on immune cells and on cancer." (PMID 33673338, 2021). "The roles of AHR in cancer were analyzed in several previous studies." (PMID 34784845, 2021). "Taken together, these findings suggest that activation of the Kyn-AHR pathway is a common feature of IDO or TDO-expressing cancers and may provide a novel immunoregulatory mechanism associated with resistance to checkpoint inhibition." (PMID 32782249, 2020). "For the relationship between AhR rs2066853 polymorphism and cancer risk, a stable trend of no significant results was identified among the overall sample in any of genetic models." (PMID 33278884, 2020). "In cancer, the AHR appears to do the opposite, i.e., to suppress apoptosis." (PMID 33396563, 2020). "Importantly, previous studies suggested the indirect role of AhR signalling in cancer promotion, progression and metastasis by affecting kynurenine pathway and immune response." (PMID 31659416, 2020). "Particular focus is placed on the association between AHR activity and poor cancer outcomes, feedback loops that control chronic AHR activity in cancer, and the role of chronically active AHR in driving cancer cell invasion, migration, cancer stem cell characteristics, and survival." (PMID 33396563, 2020). "Links between the kynurenines and cell motility come from research into the AHR and cancer." (PMID 32153556, 2020). "Relatively recent studies in cancer cells suggest that the AHR may play a role in that resistance to death." (PMID 33396563, 2020). "However, the ongoing accumulation of data from an ever-expanding variety of studies on cancer, cancer immunity, autoimmunity, organ development, and other areas bears witness to a staggering array of AHR-controlled normal and pathological activities." (PMID 33396563, 2020). "Importantly, the AHR is also constitutively active and overexpressed in many types of cancer, and CYP1A1 and CYP1B1 are overexpressed in many cancers." (PMID 32398692, 2020). "This interaction with an AhR agonist could transform the AhR into its DNA-binding form in order to stimulate the growth of cancer cells." (PMID 32957545, 2020).
cancer (continued). "This could have important implications for the consequences of even brief exposures to environmental AHR ligands and, conversely, for the use of AHR inhibitors as cancer therapeutics." (PMID 33396563, 2020). "Future studies targeted at defining AHR-independent roles of kynurenine and its catabolites could be key to fully comprehend the effects of the kynurenine pathway in cancer." (PMID 31922097, 2020). "This meta-analysis provides evidence that the rs2066853, rs7796976, or rs2074113 polymorphism in AhR gene is not a susceptible predictor of cancer." (PMID 33278884, 2020). "In addition to mediating the toxicity of environmental chemicals and regulating cellular homeostasis, AHR has been thoroughly investigated in cancer." (PMID 33260776, 2020). "When AhR is activated, it can effectively inhibit the growth of cancer cells." (PMID 33542691, 2020). "TDO might support cancer metastasis and progression of disease by affecting anti-cancer immunity or by promoting growth via AHR activation." (PMID 32050636, 2020). "The activation of AhR often contributes to clonogenicity and invasiveness of cancer cells." (PMID 32325928, 2020). "KYNs/AhR signaling has remarkable effects on the immune response during cancer progression." (PMID 32957545, 2020). "Interestingly, AhR expression in the tumors of the mice showed the same characteristic of human cancers." (PMID 31936153, 2020). "Our results demonstrate that AhR rs7796976 or rs2074113 polymorphism does not confer susceptibility to cancer." (PMID 33278884, 2020). "Overall, AhR effects will be significantly modulated by the interactions of acetyl-CoA levels, N-ASph, melatonin, miR-155, and COX2-PGE2 with consequences for SPM induction and anti-viral/cancer cell OXPHOS, glycolysis, and associated cytotoxicity." (PMID 32867244, 2020). "While a limited number of rare AHR polymorphisms were identified, none appeared to play a key role in human cancer." (PMID 33396563, 2020). "Thus, further investigations using relevant in vitro and in vivo models are warranted in order to elucidate the potential effect of the AHR in cancer spreading." (PMID 33203443, 2020). "Seeing that IDO1 inhibitors are promising for BC treatment and that MT can activate AHR, a transcription factor involved in the progression of some types of cancer, we have raised the possibility that MT activates AHR in BC cells, pointing it as inadequate to treat this type of cancer." (PMID 32907554, 2020). "Interestingly, AhR staining was more intense in cancer infiltrating cells, suggesting a role of the receptor in the invasion processes." (PMID 31936153, 2020). "Consequently, kynurenine activation of the AhR affords protection within cancer cells and acts to induce ‘exhaustion’ in cytolytic cells, with effects involving the upregulation of COX2 and PD-1." (PMID 33375613, 2020). "Studies on cancer cell lines revealed upregulated AhR levels." (PMID 32899152, 2020). "Another plausible explanation of the negative findings on rs2066853 polymorphism is that the solitary polymorphism in AhR merely influences the transcription of CYP1A1 gene but does not play a vital role in the subsequent pathway to cancer development." (PMID 33278884, 2020). "The intersection of differentially expressed genes (DEG) and our list of candidate genes, resulted in 12 elements including cancer associated genes (NRAS, MYC, and VEGFA), circadian drug targets (SOD2 and CES2) and core-clock and ECCN genes (AHR, CREB1, CSNK2A1, NFIL, NPAS2, NR1D1, and PER3)." (PMID 32295075, 2020). "Therefore in the aspect of cancer therapy, different strategies are tried, nevertheless, selective AhR modulators would be preferable in the individualized therapy." (PMID 32899152, 2020). "Induction of CYP1 family proteins and the activation of AhR will likely lead to the development of cancer and may do more harm in the long run." (PMID 31998435, 2020).
cancer (continued). "Furthermore, AhR siRNA downregulated CYPs, and inhibited cancer cell invasion together with the downregulation of the MMPs." (PMID 32443455, 2020). "Studies have found that many drugs used as AhR activators have certain anti-cancer activities." (PMID 33542691, 2020). "The role of AHR in cancer progression and metastasis is complex and still controversial." (PMID 33203443, 2020). "However, recent studies suggest that AhR plays important roles in normal physiology and pathophysiology, notably cancer." (PMID 32085612, 2020). "However, the expression level of AhR is rather heterogeneous, and varies greatly depending on the tissue, cell line and cancer category." (PMID 32085612, 2020). "AhR plays a central role in kynurenine-mediated impacts to cancer progression and cancer immunity." (PMID 32824193, 2020). "Besides playing critical roles in the initiation, promotion, progression, and metastasis of cancer, AHR is involved in the regulation of two NADases, contributing to decreased SIRT1 activity and the deregulation of glucose and fatty acid homeostasis as well." (PMID 32117717, 2020). "This AHR activity is readily identified by nuclear AHR localization in bladder, cervical, brain, pancreatic, head and neck squamous, lung adeno, lung squamous and skin carcinomas." (PMID 33396563, 2020). "Furthermore, AHR affects multiple aspects of cancer biology, including cell survival and proliferation." (PMID 31552251, 2019). "Likewise, several contaminants like dioxin, BaP and 7,12-dimethylbenz [a] anthracene (DMBA) trigger the transcription of pro-carcinogenic genes binding to and activating AHR toward cancer cell proliferation, invasion and drug resistance." (PMID 31370872, 2019). "Furthermore, the effects of AhR in cancer have been extensively discussed with an apparent conflict between its protumorigenic and anti-tumorigenic impacts." (PMID 31212758, 2019). "Furthermore, a siRNA for AhR downregulated CYPs and inhibited cancer cell invasion accompanied by the downregulation of MMP in 786-O cells." (PMID 31488157, 2019). "Worthy, it has been also demonstrated that upon activation by ligands, including 3MC, AHR triggers stimulatory effects in cancer cells through a functional cooperation with the estrogen receptor α (ERα) and other transduction pathways as growth factor receptors." (PMID 31370872, 2019). "However, P450 inhibitors have the potential for inducing the over-expression of P450 enzymes by activating the aryl hydrocarbon receptor (AhR) limiting their use as clinical cancer preventive agents." (PMID 31022888, 2019). "AhR activation via endogenous ligands can represent a critical event in human carcinogenesis and can result in the development of immune tolerance and increased survival of cancer cells." (PMID 31035533, 2019). "Thus, it is plausible that there is a close link between the anti-cancer effects of urolithins and AHR antagonism in humans." (PMID 30501068, 2018). "The AhR pathway can cross talk with other major signaling pathways that might be modulated by oncometabolites that are critical in cancer progression." (PMID 29706625, 2018). "The AhR may affect the proliferation, tissue invasion, metastasis, and angiogenesis of cancer cells." (PMID 29487603, 2018). "Even though the AHR appears to drive expression of these two MMPs, it would be premature to conclude that AHR regulation of MMPs in specific is responsible for the failure of multiple human cancer cell lines to metastasize in zebrafish." (PMID 29735912, 2018). "Moreover, the radioresistant sublines display high levels of oncometabolites including α-ketoglutarate, and treatment of cancer cells with α-ketoglutarate enhances their stem-like properties in an AhR activation-dependent manner." (PMID 29706625, 2018). "Hence, the AhR can reduce cell–cell contact and adhesion and increase the motility and invasiveness of cancer cells, which finally results in the invasion and metastasis of cancer cells." (PMID 29487603, 2018).